LGMN (legumain)
Diseases named in the same sentence as LGMN in open-access papers (continued):
Sharing a sentence is not in itself a finding about the gene and the disease.
gastric cancer (continued). "Our results suggest that Legumain might be a novel molecular marker for gastric cancer." (PMID 24023813, 2013). "We propose that Legumain could serve as a biomarker to predict prognosis in patients who undergo curative gastrectomy, and further studies are needed to clarify the role of Legumain in the progression of gastric cancer." (PMID 24023813, 2013). "First, we disrupted ACE2, TMPRSS2, and LGMN in the gastric carcinoma cell line NCC-Stk-K140, which expresses moderate levels of ACE2, low levels of TMPRSS2, and high levels of LGMN and serves as a potential model system for SARS-CoV-2 infection of the gut." (PMID 40674406, 2025). "Legumain (LGMN) has been shown to be a tumor-promoting protein, but the effect of LGMN on TAMs in the progression of gastric cancer (GC) is under exploration." (PMID 31892854, 2020). "It has also been shown that legumain facilitates epithelial to mesenchymal transition (EMT) and metastatic progression in gastric cancer through activation of MAPK and Akt signaling pathways and overexpressed in different cancers." (PMID 27793040, 2016). "Similar results were seen by monitoring 73 patients with stomach cancer and discovered a negative connection between LGMN expression and cumulative survival." (PMID 36825203, 2023). "Legumain both expressed in noncancerous mucosa, primary gastric cancer tissue, and metastasis lymph nodes." (PMID 24023813, 2013). "Legumain was significantly over-expressed in primary gastric cancer with metastasis than without metastasis." (PMID 24023813, 2013). "In summary, it has been shown highly expressed of Legumain has a negative influence on prognosis and a positive correlation with metastasis of gastric carcinoma, possibly through increased extracellular matrix degradation." (PMID 24023813, 2013). "However, the precise mechanism about what induces legumain expression during metastatic progression of gastric cancer is not known, which was the objective of the present study." (PMID 27793040, 2016). "Legumain expression exhibited negative or diffuse weakly positive staining in the cytoplasm in distant normal mucosa and exhibited strong vesicular positivity in the cytoplasm in primary gastric cancer." (PMID 24023813, 2013). "However, not much is known beyond expression pattern of legumain and PCBP1 during peritoneal metastasis of gastric cancer patients." (PMID 30246786, 2018).
colorectal cancer (13 papers, 2013 to 2025). A primary or metastatic malignant neoplasm that affects the colon or rectum. "Given the high levels of legumain associated with colorectal cancers, it is likely to play similar cancer‐promoting roles in the landscape of chronic gut inflammation." (PMID 39392222, 2025). "In the A/J Min mice model for colorectal cancer, animals treated with AndosanTM had reduced intestinal tumor load, and also expressed less of the tumor-associated protease, legumain, in their intestines." (PMID 32397163, 2020). "Collectively, these results shed light on potential functions of legumain and highlight its potential roles in the transition from inflammation to colorectal cancer." (PMID 39392222, 2025). "Legumain localizes to the nucleus in the setting of colorectal cancer and can cleave the nuclear protein FOXP3 in regulatory T-cells to inhibit T-cell differentiation." (PMID 38199506, 2024). "This is supported by findings that tunicamycin treatment of human colorectal carcinoma cells increased the secretion of less active (and less stable) legumain, which had lost its ability to be autoactivated." (PMID 38092995, 2023). "Although legumain is mainly located in the endolysosomes, both pro- and active legumain have been detected in the nucleus and cytosol of colorectal cancer cells." (PMID 36555634, 2022). "In contrast, the RKO cell line showed simultaneous high expression of inactive (30 kDa, single chain) cathepsin L and a lower level of active legumain, suggesting that these cysteine proteases are subjected to mutual activation in colorectal cancer cell lines." (PMID 23326369, 2013). "As such, legumain may promote the development of colorectal cancer through promoting Prodh expression." (PMID 39392222, 2025). "For LGMN, in addition to its lysosomal localization and observed secretion, a localization in the nucleus has been described in colorectal cancer patients suggesting that LGMN might work as a transcription factor as reported in plants." (PMID 35053409, 2022). "In the present work, legumain expression was examined in colorectal cancer cell lines." (PMID 23326369, 2013). "In situ analyses of legumain expression and activity confirmed the endo-lysosomal and nuclear localizations in cultured cells and, importantly, also in sections from xenografts and biopsies from colorectal cancer patients." (PMID 23326369, 2013). "In this study, legumain expression and proteolytic activity were examined in two colorectal carcinoma (CRC) cell lines, HCT116 and SW620." (PMID 23326369, 2013).
atherosclerosis (9 papers, 2015 to 2025). A disease characterized by the build-up of fatty material and calcium deposition in the arterial wall resulting in partial or complete occlusion of the arterial lumen. "In conclusion, the present study demonstrated that legumain affects the progression of atherosclerosis by modulating CD4+ T cell biology, which is a novel immunological molecular mechanism of legumain in the pathogenesis of atherosclerosis." (PMID 39473192, 2025). "LGMN promotes the synthesis of ECM components in PAH and the degradation of ECM components in atherosclerosis, further demonstrating the key role of LGMN in tissue remodeling." (PMID 39104790, 2024). "The mechanism of action of LGMN and its roles as a therapeutic target and biomarker of atherosclerosis-related diseases deserve further study." (PMID 39104790, 2024). "Legumain is expected to emerge as a novel therapeutic target for atherosclerosis and related diseases." (PMID 31060209, 2019). "Legumain deficiency impairs TCR signaling, CD4+ T cell survival and proliferation, and reduces the formation and function of effector T cells in Apoe−/− mice, conferring protection against atherosclerosis." (PMID 39473192, 2025). "The mechanism of action of LGMN in atherosclerosis is complex." (PMID 39104790, 2024). "On the other hand, the benefit of targeting legumain in atherosclerosis therapy may be its effect on inflammation." (PMID 34961842, 2021). "Low molecular weight inhibitors and neutralizing antibodies against legumain may become promising candidate drugs for the treatment of atherosclerosis." (PMID 31060209, 2019). "However, the role and function of legumain in T cells in cardiovascular disease, particularly in the progression of atherosclerosis, remain unclear." (PMID 39473192, 2025). "Therefore, targeting legumain in specific cells or tissues may be a potential therapeutic strategy to control the progression of atherosclerosis." (PMID 39473192, 2025). "In conclusion, our study suggests that legumain plays a key role in regulating CD4+ T‐cell function and the progression of atherosclerosis." (PMID 39473192, 2025). "As a member of the cysteine protease family, legumain (LGMN) augments the occurrence and development of atherosclerosis, pulmonary hypertension, peripheral vascular disease, aortic aneurysm and dissection, and promotes the outcome of coronary heart disease." (PMID 39104790, 2024).
Cognitive impairment (9 papers, 2020 to 2025). Abnormal cognition is characterized by deficits in thinking, reasoning, or remembering. "In fact, a number of recent studies implicated knockouts of the asparagine endopeptidase legumain in improved cognitive impairment and neuroprotection, in the context MCAO." (PMID 37597109, 2023). "The therapeutic targeting of legumain has been proposed as a novel strategy in the treatment of AD, as legumain deficiency is shown to inhibit neuroinflammation and protect against Aβ-induced cognitive deficits and synaptic plasticity dysfunction." (PMID 36555634, 2022). "In a mouse model mimicking chronic cerebral hypoperfusion, the depletion of legumain improved cognitive impairment by reducing neuroinflammation, as legumain is upregulated and triggers synaptic plasticity impairment and neuroinflammation." (PMID 36555634, 2022).
glioblastoma (8 papers, 2021 to 2025). The most malignant astrocytic tumor (WHO grade IV). "There has also been a study that demonstrates the inhibitory effect of CLOCK on glioblastoma through the OLFML3-HIF1α-LGMN pathway." (PMID 38703241, 2024). "TAM-derived legumain exerts dual regulatory roles in glioblastoma (GBM) by promoting macrophage infiltration in an autocrine manner via the GSK3β/STAT3 pathway, while in a paracrine fashion, TAM-secreted legumain drives GBM cell proliferation and survival through integrin αv/AKT/p65 signaling." (PMID 41417432, 2025).
colon carcinoma (7 papers, 2013 to 2025). "Outside of gastric and colon cancer, little has been reported on the roles of legumain within the gastrointestinal tract." (PMID 39392222, 2025). "In fact, in the mouse model for colon cancer, Andosan did also induce reduced expression of legumain in the intestinal wall." (PMID 29238712, 2017). "Legumain is a promising target as it is expressed on CD206+/F4/80+ TAMs and a legumain-based DNA vaccine induced a robust CD8+ T cell response against TAMs in murine models of metastatic breast cancer, colon cancer and non-small cell lung cancer." (PMID 32983125, 2020). "Therefore, discrepancy in cystatin E/M expression can probably not explain the observed differences in mature 36 kDa legumain between the two colon cancer cell lines." (PMID 23326369, 2013).
melanoma (7 papers, 2010 to 2025). A malignant, usually aggressive tumor composed of atypical, neoplastic melanocytes. "Moreover, in another example, a study on glucose dependent melanoma found that high LGMN expression was associated primarily with local invasion by the tumor." (PMID 38980440, 2024). "Invasion is suppressed in cystatin M/E overexpressing melanoma cell lines and intracellular legumain activity is drastically impaired." (PMID 33919854, 2021). "Conversely, CatB activity is not affected, which suggests that cystatin M/E specifically regulates legumain activity and therefore the invasive potential of human melanoma cells." (PMID 33919854, 2021). "Recently, we screened a panel of melanoma cell lines and found that legumain was expressed and active in most of the cell lines investigated." (PMID 23326369, 2013). "Previously, we have reported an inverse correlation between secreted 17 kDa cystatin E/M and active legumain in melanoma cells." (PMID 23326369, 2013). "Further studies are needed to elucidate the role of both cystatin E/M and legumain in melanoma, including their expressions during different stages of the disease and their roles in tumor formation and metastasis in vivo." (PMID 20074384, 2010). "MCC11 is a low-passage melanoma line established from a patient's lymph node metastases showing a high level of the 36 kD form of legumain." (PMID 20074384, 2010). "In general, high legumain expression and activity was revealed in the examined panel of melanoma cell lines." (PMID 20074384, 2010). "A375 is a commonly used melanoma cell line, with intermediate expression of the 36 kD form of legumain." (PMID 20074384, 2010). "Collectively, our data strongly suggests that cystatin E/M inhibits melanoma progression by suppressing legumain activity." (PMID 20074384, 2010). "In this study, we provide data indicating that cystatin E/M suppresses invasiveness of melanoma cells, likely via the inhibition of the cysteine protease legumain known to be present in metastatic lesions." (PMID 20074384, 2010). "Legumain, cathepsin B and L were expressed and active in most of the cell lines, although at low levels in the melanomas expressing cystatin E/M." (PMID 20074384, 2010). "In summary, we characterized tumor-induced changes in the DC2 proteome of which several are associated with immunosuppression and protumor effects, including IDO1 and LGMN, through which melanoma-induced DC3s could impair antitumor immunity." (PMID 40789452, 2025). "Interestingly, epithelial-type tumors and melanomas displayed a predominant vesicular positivity of legumain." (PMID 35203212, 2022). "Over-expression of cystatin E/M, a legumain inhibitor, suppresses melanoma cell invasion." (PMID 29541256, 2018). "We have observed expression of cystatin E/M, legumain, cathepsin B and L in multiple melanoma cell lines, and an inverse correlation between secreted levels of the cysteine protease inhibitor and cellular activities of legumain and cathepsin B (but not cathepsin L) was detected." (PMID 20074384, 2010). "Interestingly, those melanoma cell lines from patients showing a strong expression of the 36 kD active legumain form, seemed to have a stronger expression of the 25 kD active cathepsin L form compared to the 30 kD form, although not statistically significant." (PMID 20074384, 2010). "Although the activities of cathepsin B and L in melanoma and other tumor types are well documented, the expression and activity of legumain in melanoma is relatively unknown." (PMID 20074384, 2010). "We conducted a proteome analysis of DC2s in tumor-free conditions compared to DC2s cultured with melanoma-secreted factors, revealing increased IDO1 and LGMN in ti-DC3s." (PMID 40789452, 2025). "By immunoblotting, we detected cystatin E/M secretion from four melanoma cell lines (MCC13, 57, 70 and 72), and the conditioned media from these cells demonstrated the highest inhibitory activities against legumain." (PMID 20074384, 2010).
melanoma (continued). "When melanoma cells lacking secretion of cystatin E/M were transfected with pCST6, their intracellular legumain activity was significantly inhibited." (PMID 20074384, 2010). "In our study, comparisons of band intensities of legumain and cathepsin L did not statistically correlate, but the melanoma cell lines derived from patient biopsies seemed to express a stronger 25 kD mature cathepsin L immunoband in the cell lines with a strong 36 kD active legumain band." (PMID 20074384, 2010).
ovarian carcinoma (7 papers, 2015 to 2025). A malignant neoplasm originating from the surface ovarian epithelium. "In epithelial ovarian cancer cells, α5β1 integrin is highly expressed and co‐localized with asparaginyl endopeptidase (AEP), also known as the zymogen‐like endosomal protease legumain." (PMID 40327521, 2025). "From their research following patients with ovarian cancer, It was concluded that those with high LGMN expression were more likely to have a poor outcome than those with low expression." (PMID 36825203, 2023). "Although the presence of LGMN in exosomes has not yet been studied in MM, LGMN mRNA has been described in secreted exosomes in pancreatic cancer and an integrin/AEP complex in ovarian cancer." (PMID 35053409, 2022).
Stroke (7 papers, 2011 to 2023). Sudden impairment of blood flow to a part of the brain due to occlusion or rupture of an artery to the brain. "In addition, it is shown that legumain contributes to the immune responses during stroke by indirectly altering the number of CD74+ cells in the ischemic hemisphere by the modification of molecules involved in immune cell attraction." (PMID 36555634, 2022). "Increased legumain expression in the peri-infarct area was observed after transient occlusion of the middle cerebral artery; however, legumain was not essential for the functional deficit in a rat stroke model." (PMID 36555634, 2022).
myocardial infarction (6 papers, 2020 to 2025). Gross necrosis of the myocardium, as a result of interruption of the blood supply to the area, as in coronary thrombosis. "In contrast, during myocardial infarction, LGMN deficiency increases macrophage infiltration and monocyte recruitment." (PMID 39104790, 2024). "LGMN deficiency worsens cardiac function after experimental myocardial infarction associated with accumulations in apoptotic cardiomyocytes, owed to impairments in efferocytosis in the border area." (PMID 36710920, 2023). "LGMN knockout resulted in the accumulation of apoptotic cardiomyocytes and exacerbated myocardial infarction." (PMID 39104790, 2024). "The development and prognosis of myocardial infarction can be improved by regulating the function of LGMN, which will require more studies to clarify the function of LGMN in disease occurrence, progression, and recovery." (PMID 39104790, 2024). "Macrophage secretion of LGMN was required to promote the efferocytosis of apoptotic cardiomyocytes in myocardial infarction, and selective overexpression of LGMN by macrophages improved cardiac function in mice after myocardial infarction." (PMID 39104790, 2024). "Whereas Legumain has been shown to be critical for the resolution of fibrosis after murine myocardial infarction and obstructive nephropathy, its role in regeneration had not been previously explored." (PMID 37726321, 2023). "Thus, prospective studies with larger cohorts are needed to clarify the predictive role of LGMN in acute myocardial infarction patients." (PMID 39104790, 2024). "Given the ability of legumain to promote tissue repair after myocardial infarction and the potential splenomegaly and erythropoiesis that may result from legumain downregulation, low levels of legume protease expression may be beneficial and should be further investigated." (PMID 39473192, 2025). "Legumain (LGMN), which resides in lysosomes and endosomes and hydrolyzes asparaginyl bonds, plays an interesting role in continual efferocytosis, particularly after myocardial infarction." (PMID 36710920, 2023). "In animal studies, the LGMN inhibitor RR-11a was found to improve myocardial remodeling and reduce the rate of cardiac rupture by inhibiting ECM degradation, demonstrating that LGMN may be a therapeutic target for myocardial infarction." (PMID 39104790, 2024).
acute kidney injury (4 papers, 2022 to 2025). Sudden and sustained deterioration of the kidney function characterized by decreased glomerular filtration rate, increased serum creatinine or oliguria. "LGMN knockout inhibits the upregulation of proinflammatory cytokines in ischemia-reperfusion injury (IRI) induced acute kidney injury, providing evidence of the involvement of LGMN in the proinflammatory response." (PMID 39104790, 2024). "Legumain has been shown to facilitate tubular ferroptosis via the promotion of chaperone-mediated GPX4 autophagy in acute kidney injury, while the selenium-GPX4 axis reduces the ferroptosis of follicular helper T cells." (PMID 35805124, 2022). "Furthermore, in IRI or folate-induced acute kidney injury (AKI) models, HSC70-HSP90-GPX4 interacts with legumain in the kidney to promote chaperone mediated degradation of GPX4, thereby promoting renal tubular cell ferroptosis in AKI." (PMID 35478955, 2022).
carotid atherosclerosis (4 papers, 2019 to 2025). A thickening and loss of elasticity of the walls of carotid arteries that occur with formation of atherosclerotic plaques. "The secretion of mature human legumain (HsLMN) has been linked to carotid atherosclerosis." (PMID 40109889, 2025). "Recent clinical studies have shown that legumain is expressed in carotid plaques and is present at a high concentration in the plasma of patients with carotid atherosclerosis." (PMID 31060209, 2019). "Legumain, a recently discovered cysteine protease, is increased in both carotid plaques and plasma of patients with carotid atherosclerosis." (PMID 31060209, 2019).